OPA1 (OPA1 mitochondrial dynamin like GTPase)
Diseases named in the same sentence as OPA1 in open-access papers (continued):
Sharing a sentence is not in itself a finding about the gene and the disease.
tumor (64 papers, 2015 to 2026). "Conversely, mitochondrial fusion proteins MFN1, MFN2, and OPA1 have also been associated with tumor progression." (PMID 41146909, 2025). "In different tumor tissues, there was a notable positive correlation between OPA1 expression levels and the infiltration of cancer-associated fibroblasts in the immune microenvironment." (PMID 37980164, 2023). "In the present study, we investigated the mutation of the OPA1 gene in tumors and its relationship with the prognosis of tumor patients." (PMID 37980164, 2023). "We employed the TIMER 2.0 database to explore the correlation between OPA1 expression levels in tumor tissue and the infiltration of cancer-associated fibroblasts in the immune microenvironment." (PMID 37980164, 2023). "In LUAD, the mitochondrial fusion process caused by OPA1 is activated, enhancing mitochondrial metabolism to promote tumor growth and inhibit apoptosis." (PMID 37980164, 2023). "High expression of OPA1 in primary tumors was associated with shorter metastasis-free survival after surgery, and low expression of OPA1, with anti-tumor immune signatures." (PMID 37024121, 2023). "Our study indicates a significant presence or mutation of OPA1 in various tumors, demonstrating strong correlations with protein phosphorylation, patient prognosis, immune cell infiltration, and tumor mutational load." (PMID 37980164, 2023). "Both of OPA1 and MFN1 were highly expressed in LUAD tumor tissues and OPA1 high expression was associated with poor prognosis." (PMID 36573240, 2022). "Our findings suggest that OPA1 is highly expressed or mutated in a variety of tumors and is strongly associated with protein phosphorylation, patient prognosis, immune cell infiltration, and tumor mutational load." (PMID 37980164, 2023). "Furthermore, proteins associated with mitochondrial fusion, such as Mfn1/Mfn2 and Opa1, have been recently reported as essential players for tumor angiogenesis as they increase the oxygen consumption and cellular ATP production in liver cancer cells." (PMID 36827549, 2023). "Mechanistically, it was found that loss of OPA1 increased cytosolic Ca2+, activating NFκB, reducing key angiogenic gene expression, and inhibiting tumor vasculature leading to a significant reduction in tumor growth and metastasis." (PMID 35356277, 2022). "Analyzing from a mitochondrial perspective, we found that the morphology-related protein OPA1 may be one of the key factors for celastrol to inhibit tumor angiogenesis, thus we constructed OPA1-deficient HUVECs with siRNA to verify this conjecture." (PMID 36678677, 2022). "The tubular network of mitochondria meditated by OPA1 favors tumor cell proliferation signals that may be linked to c-Myc activation." (PMID 34868997, 2021). "In fact, loss of PHB2 is strongly associated with accelerated OPA1 processing, as well as impaired cell proliferation and apoptosis while an over-expression of PHBs is reported to protect cells from apoptosis, and it was found in several tumor cells." (PMID 31547300, 2019). "Although studies have indicated that OPA1 is a key gene involved in the process of mitochondrial fusion, the loss of which will block the process of metabolism in tumor cells, the underlying mechanism remains poorly defined, and the detailed function of OPA1 in LUAD development remains unknown." (PMID 36573240, 2022). "The intraperitoneal injection of DdBIC significantly suppressed tumor growth (top), with related events, including GSDMC and OPA1 cleavage, eIF2α phosphorylation, and a decrease in heme levels, detected in the same tumor samples (bottom)." (PMID 41407678, 2025). "In the tumor tissues of liver cancer patients, larger mitochondria were observed, accompanied with raised expression of OPA1 and Mfn1, indicating enhanced mitochondrial fusion in tumor tissues, which promoted metabolism and tumor growth." (PMID 40500258, 2025).
tumor (continued). "These miRNAs inhibit tumor growth and invasiveness and likely contribute to the selective effects of OPA1 deletion/inhibition on the metastatic properties of CA1a and CA1h cells." (PMID 40691145, 2025). "Further validation from biopsies obtained from a human biobank confirmed the heightened expression of OPA1/3 specifically in tumor tissues." (PMID 38911373, 2024). "Both OPA1 and MFN1 exhibit high expression levels in LUAD tumor tissues, with elevated OPA1 expression correlating with poor prognosis." (PMID 38911373, 2024). "Studies have demonstrated that inhibition of MIF expression in tumor cells leads to down-regulation of OPA1 and MFN1 while up-regulating DRP1 expression, resulting in mitochondrial fragmentation." (PMID 38405130, 2024). "Mechanistically, OPA1 knockdown alters cristae morphology and inhibits electron transport chain assembly and activity, resulting in impaired tumor cell proliferation due to decreased NAD+ regeneration." (PMID 38911373, 2024). "High OPA1 in CSCs was confirmed with immunoblot, showing approximately 5-fold higher relative intensity in tumor spheres." (PMID 36809297, 2023). "Based on the median expression level of OPA1 in tumor cells of tumor patients, we divided the patients into high and low-expression groups." (PMID 37980164, 2023). "The delayed tumor growth by C75 was OPA1 dependent, as overexpression of OPA1 significantly blocked the inhibitory effect of C75." (PMID 36809297, 2023). "Genetic knockdown of SPDEF using siRNA efficiently reduced OPA1 expressions in tumor spheres, supporting SPDEF-instructed high OPA1 in CSCs." (PMID 36809297, 2023). "Compared with MFN1 and MFN2, which were slightly elevated in tumor spheres, the transcriptome of OPA1 was dramatically increased in CSCs." (PMID 36809297, 2023). "The OPA1 protein regulates tumor growth through the modulation of angiogenesis and apoptosis, but its contribution to tumor cells themselves has not been documented." (PMID 37024121, 2023). "Next, we turned to MYLS22, a specific Opa1 inhibitor recently developed in our lab that curtails Opa1-dependent tumor angiogenesis and growth and is efficacious against TNBC cells in vitro and in vivo." (PMID 37019897, 2023). "This type of signature evokes that found in the OMA1 mutant model that was developed in which stress-induced OPA1 cleavage is prevented, limiting adaptation to mitochondrial stress of tumor cells and exposing to increased immunogenic cell death." (PMID 37024121, 2023). "OPA1-depleted tumor spheres also exerted delayed tumorigenicity and compromised outgrowth in NSG mice." (PMID 36809297, 2023). "Inner membrane protein OPA1 is required for tumor vascularization, metastasis and growth, and ECs angiogenesis by maintaining cytosolic Ca2+ buffering through interacting with MICU1 and inhibiting NF-κB, which activated the pro-angiogenic gene expression." (PMID 37407961, 2023). "To this end, we analyzed OPA1 expression, genetic alterations, patient survival prognosis, and immune infiltration in a total of 33 different tumor species based on an online database." (PMID 37980164, 2023). "Genetic knockdown of OPA1 using siRNA efficiently reduced OPA1 expressions, impairing mitochondrial fusion in tumor spheres." (PMID 36809297, 2023). "Then use the Kaplan-Meier plotter to analyze and visualize the survival of tumor patients with different OPA1 expression levels at different periods." (PMID 37980164, 2023). "OPA1 holds promise as a novel prognostic marker with potential clinical utility across various tumor types." (PMID 37980164, 2023). "The transcription of Opa1 and Marf increases in brat RNAi and expression of Opa1 and Marf is important for proliferation of tumor NBs." (PMID 35157701, 2022). "Our present work further reveals that knockdown of OPA1 mediated high expression of immune response related genes contributes to the cell–cell communication of tumor epithelial and T cells." (PMID 36573240, 2022).
tumor (continued). "By comparing the interaction network between OPA1+ and OPA1− tumor tissues, we found that the communication of tumor epithelial with CD8+ T cells was significantly increased in OPA1− tumor tissues." (PMID 36573240, 2022). "Reduction in the angiogenic capacity of the endothelial cells—mediated by an endothelial cell specific OPA1 knockout—significantly reduced primary tumor growth and metastasis in melanoma models." (PMID 35356277, 2022). "OPA1 protein levels were not significantly affected by the growth of the C26 tumor, whereas MitoQ was able to upregulate the expression of OPA1 in the muscle of both healthy and tumor-bearing mice." (PMID 35392166, 2022). "Together, these data suggest that mitochondrial fission is dispensable for KP LUAD development in vivo, and that Opa1 is essential in tumor cells with intact mitochondrial fission." (PMID 36516772, 2022). "Second, we isolated independent tumor cell lines from mice to assess the presence of Drp1 and Opa1 by immunoblot and PCR." (PMID 36516772, 2022). "Together, these data suggest that Drp1 is dispensable, but Opa1 is required, for KP LUAD development, and that deletion of Drp1 is insufficient to rescue Opa1 deletion-mediated decrease in tumor development in vivo." (PMID 36516772, 2022). "All cells were divided into 19 clusters according to the t-SNE clustering algorithm and exhibited a higher expression of OPA1 in tumor epithelial cell." (PMID 36573240, 2022). "We cultivated tumor cells with bone marrow-derived macrophages of wild-type or Opa1-/- or their conditioned media." (PMID 36517518, 2022). "Immunohistochemical results also revealed that the protein expression of OPA1 was significantly increased in LUAD tumor tissues." (PMID 36573240, 2022). "Our results support a model in which mitochondrial fission events disrupt cristae structure, and tumor cells with hyperactive fission activity require Opa1 activity to maintain ETC function." (PMID 36516772, 2022). "Mechanistically, Opa1 deletion impacts colony formation and tumor growth through disruption of cristae morphology and inhibition of ETC assembly and function." (PMID 36516772, 2022). "In summary, our results showed that the process of mitochondrial fusion caused by OPA1 was activated in LUAD, which enhanced mitochondrial metabolism to fuel tumor growth and inhibited cell apoptotic pathways." (PMID 36573240, 2022). "Consistent with this, six of seven individually derived KPD tumor cell lines exhibit no detectable Drp1 by immunoblot, while all seven independently derived KPO tumor cell lines retain lower, but detectable, expression of Opa1." (PMID 36516772, 2022). "The previous reports demonstrate that OPA1 plays an important role in tumor angiogenesis, which provides stronger evidence to validate the promising capacity of celastrol in anti-tumor angiogenesis therapy." (PMID 36678677, 2022). "Mechanistically, Opa1 knockout disrupts cristae morphology and inhibits electron transport chain (ETC) assembly and activity, which inhibits tumor cell proliferation through loss of NAD+ regeneration." (PMID 36516772, 2022). "Important for our study, also overexpression of OPA1 was shown to reduce cell migration and invasion in multiple cancer types and even tumor progression in vivo." (PMID 34674701, 2021). "Significant decrease in the relative expression of the mitochondrial genes COXIV and OPA1 was also observed in gastrocnemius samples from tumour-bearing mice." (PMID 33975599, 2021). "Emerging evidence indicates that hepatocellular carcinomas have higher levels of OPA1 expression compared to non-tumor tissues." (PMID 34868997, 2021). "Upon subcutaneous engraftment in immunodeficient nude mice, we demonstrated that knockdown of OPA1 or MFN1 dramatically inhibited tumor formation and growth of HCC cells in vivo." (PMID 31947947, 2020). "In contrast, the Exon4b-containing OPA1 isoforms were markedly decreased in tumor tissues (p = 0.0007)." (PMID 32373606, 2020).
tumor (continued). "When marf or opa1 was knocked down in Hipk tumor-like cells, most mitochondria appeared dot-like (I-I′′)." (PMID 33199523, 2020). "We found that the level of OPA1-Exon4b was downregulated in HCC tumor tissues and that Exon4b silencing compromised Δψm in an HCC cell line." (PMID 32373606, 2020). "To further confirm the effect of Niclosamide on OPA1 cleavage in vivo, we analyzed OPA1 level in mock and Niclosamide administrated nude mice tumor sections and found OPA1 was cleaved which was consistent with the data in vitro." (PMID 32284741, 2020). "The knockdown of both MFN1 and OPA1 inhibited mitochondrial fusion in both experimental settings, leading to a reduced cell growth and tumor formation." (PMID 33233365, 2020). "Accumulating evidence indicates that dysregulation of OPA1 expression or activity contributes to the initiation and progression of multiple malignancies, underscoring its importance in tumor cell survival, proliferation, metabolic adaptation, and resistance to stress." (PMID 41596202, 2026). "Furthermore, we conducted a comprehensive assessment of OPA1/3 expression across different clinical stages, revealing a notable increase in their expression levels in both tumor tissues and advanced-stage patients." (PMID 38911373, 2024). "Additionally, OPA1-mediated mitochondrial fusion in endothelial cells promotes tumor angiogenesis, affecting tumor growth and metastasis." (PMID 38812059, 2024). "Notably, macrophages exhibited significant enrichment and infiltration within tumor tissues, correlating with elevated OPA1/3 expression levels." (PMID 38911373, 2024). "In addition, knockdown of Optic atrophy 1 (Opa1), a protein involved with inner mitochondrial membrane fusion, was also able to improve muscle integrity in tumour-bearing animals (QRasV12scribRNAi)." (PMID 38429578, 2024). "Furthermore, first-in-class OPA1 inhibitor MYLS22 limits tumor growth and metastatization, indicating target Opa1 is effective for inhibiting tumor angiogenesis." (PMID 37407961, 2023). "We analyzed the genetic alteration status of OPA1 in different tumor samples from the TCGA cohort." (PMID 37980164, 2023). "Furthermore, the complex functions of various OPA1 isoforms on the control of crista structure and fission would justify to complete our study with a biochemical analysis of OPA1 protein on tumor samples." (PMID 37024121, 2023). "This is because the elevated expression of OPA1 may simply be due to the alteration of normal tissues during the anti-tumor process." (PMID 37980164, 2023). "Furthermore, FASN was genetically knocked down using siRNA in tumor spheres, and this essentially inhibited the transcriptome of OPA1, resulting in a 50% reduction of OPA1 mRNA levels." (PMID 36809297, 2023). "Based on our results, one could propose to design modulators of OMA1 or OPA1 activation targeting the redox switch or the fusiogenic function of OPA1 to enhance tumor cell fragility and immunostimulation." (PMID 37024121, 2023). "We next assessed whether Opa1 deletion inhibits tumor cell growth by inhibition of mitochondrial fusion." (PMID 36516772, 2022). "In a previous study, the upregulation of OPA1 promoted tumor angiogenesis by suppressing NF-κB activation, while in this study, celastrol administration decreased OPA1, followed by p-P65 upregulation, which is the signal of NF-κB activation, thus showing the anti-angiogenesis effect." (PMID 36678677, 2022). "Moreover, inhibition of mitochondrial fusion by knock-down of Opa1 or Mfn1 inhibited cell growth and tumor formation." (PMID 35933403, 2022). "We therefore setup a proof of principle experiment to verify whether acute pharmacological OPA1 inhibition could curtail tumor growth." (PMID 35279198, 2022). "Moreover, activation of OPA1 promoted mitochondrial dynamics in tumor epithelial cells to escape CD8+ T cells killing." (PMID 36573240, 2022).
tumor (continued). "In this case, the knockdown of OPA1 or MFN1 inhibited tumor formation in vivo in mice." (PMID 35565283, 2022). "However, a recent landmark paper was published describing the importance of OPA1 in endothelial cells and how regulation of this protein in endothelial cells directly impacts tumor growth and metastasis." (PMID 35356277, 2022). "This suggests that OPA1− tumor epithelial cells may regulate the immune responses strongly, while OPA1+ tumor epithelial cells are associated with immune escape." (PMID 36573240, 2022). "Indeed, some authors have recently shown the crucial role of OPA1 in tumor cell metabolism and angiogenesis." (PMID 35884493, 2022). "Moreover, we used sigle-cell sequencing data to further analysis the immune response of OPA1+ tumor epithelial cell to immune cells." (PMID 36573240, 2022). "OPA1 has been reported to be a core molecule in tumor angiogenesis, and a series of experiments have confirmed that celastrol inhibits angiogenesis mainly by downregulating OPA1 expression, but more specific molecular mechanisms involved need to be further investigated." (PMID 36678677, 2022). "Recently, cumulative studies have revealed the function of OPA1 in tumor advancement." (PMID 34868997, 2021). "Interestingly, OPA1 has also been identified as a critical regulator of tumor angiogenesis." (PMID 41146909, 2025). "Therefore, OPA1 interacts with a variety of genes that affect tumor metastasis and prognosis." (PMID 37980164, 2023). "One report showed that the use of an OPA1 inhibitor (MYLS22) could limit tumor growth." (PMID 37024121, 2023). "The most significant observation was to show the good prognosis value of low OPA1 expression for MFS in STS and the associated presence of immune signatures linked to IFN-γ signaling, MHC expression, and infiltration by immune cells with potential anti-tumor functions." (PMID 37024121, 2023). "OPA1 deletion resulted in reduced engraftment (3/8 engrafted MDA-MB-231 OPA1−/− vs. 8/8 MDA-MB-231 OPA1−/−:OPA1), but because 37.5% of the implants attached, we could compare tumor growth that was almost nil for the MDA-MB-231 OPA1−/− compared to the MDA-MB-231 OPA1−/−:OPA1 grafts." (PMID 35279198, 2022). "However, whether cancer cells are addicted to OPA1, and its pharmacological or genetic inhibition can curtail tumor growth awaits formal testing." (PMID 35279198, 2022). "Intraperitoneal injection of DdBIC significantly reduced xenograft tumor growth in a dose-dependent manner, with GSDMC and OPA1 cleavage and eIF2α phosphorylation." (PMID 41407678, 2025). "Proteins such as OPA1, involved in mitochondrial fusion, is often amplified in LUAD, promoting tumor growth and immune evasion by maintaining mitochondrial respiratory function." (PMID 41213905, 2025). "Subsequently, we examined the mRNA expression of OPA1/3 in 25 pairs of BRCA and non-tumor tissues sourced from the KSVGH Biobank." (PMID 38911373, 2024). "The data form GENT indicated an upregulation in the expression of METTL3, RRM2B, OPA1 and IGF2BP2 in CRC tumor tissues compared with normal tissues." (PMID 38549713, 2024). "In NSCLC tumor spheres, SPDEF binds to the OPA1 gene, promoting OPA1 expression, mitochondrial fusion activity, and stem-like properties." (PMID 36809297, 2023). "In line with the essential role of mitochondrial fusion for stem-like properties, knockdown of OPA1 inhibited expressions of stem-related gene ALDH1 and OCT4 in tumor spheres, accompanied by a substantial loss of sphere-formation capacity." (PMID 36809297, 2023). "Upon OPA1 knockout in tumor cells, the researchers observed damage to mitochondrial cristae and a substantial reduction in the NAD+/NADH ratio resulting from OPA1 depletion." (PMID 37635869, 2023). "We discovered downregulation of mito-fusion protein OPA1 (mitochondrial dynamin-like 120-kDa protein) and MFN2 (mitofusin-2) and upregulation of mito-fission protein DRP1 (dynamin-related protein 1) in tumor cells with SIRT1 KO." (PMID 37063423, 2023).